TRIM71 (tripartite motif containing 71)
Diseases named in the same sentence as TRIM71 in open-access papers (continued):
Sharing a sentence is not in itself a finding about the gene and the disease.
liver cancer (continued). "Importantly, ATRA or A-485 decreased mRNA levels of TRIM71, CEBPA, PSPH, PSAT1 and protein levels of TRIM71 and CEBPA, suggesting the transcriptional regulation of RXRA and EP300 to TRIM71 in liver cancer." (PMID 39267787, 2024). "Notably, a RBP termed as tripartite motif-containing 71 (TRIM71, also known as LIN-41), which functions as a key regulator of proliferation and differentiation in stem and progenitor cells, ranked highest in both oncofetal contribution and liver cancer dependency." (PMID 39267787, 2024). "Colony formation results indicated that overexpression of full-length TRIM71 significantly promoted the clonogenic capacity of liver cancer cells Li-7 and HCCLM3 with no or less expression of TRIM71." (PMID 39267787, 2024). "Analysis of the Depmap database revealed abundant TRIM71 expression in HepG2, HuH-7, and HuH-6, whereas TRIM71 had negative expression in Li-7 and SNU-449 liver cancer cell lines." (PMID 39267787, 2024).
ovarian carcinoma (4 papers, 2019 to 2024). A malignant neoplasm originating from the surface ovarian epithelium. "Consistently, high levels of TRIM71 in ovarian carcinomas predicts favorable prognosis of ovarian cancer patients." (PMID 32660118, 2020). "Ectopic TRIM71 also restrained, whereas ablation of TRIM71 endorsed, ovarian carcinoma cell growth in vitro and in vivo." (PMID 31570706, 2019). "Altogether, our findings unveil the anti-tumor function of TRIM71 in ovarian cancer development and prognosis by downregulating mutant p53s." (PMID 31570706, 2019). "Next, we investigated the clinical relevance of TRIM71 in ovarian cancer." (PMID 31570706, 2019). "These correlations also suggest that TRIM71 might regulate ovarian cancer cell proliferation, survival, metastasis, lipid metabolism, redox homeostasis, glycolysis, proteasome pathway, and chemoresistance by antagonizing mtp53s’ GOFs." (PMID 31570706, 2019). "Hence, our studies as detailed below unravel the tumor-suppressive function of TRIM71 in ovarian cancer through inhibition of mtp53s." (PMID 31570706, 2019). "Significantly, our bioinformatics analysis of primary ovarian cancer data via online available information uncovers that TRIM71 could be a prognostic marker for ovarian cancer." (PMID 31570706, 2019). "Conversely, knockdown of TRIM71 by two independent siRNAs markedly accelerated cell proliferation, enhanced the colony-forming ability, and promoted invasion of the two ovarian cancer cell lines." (PMID 31570706, 2019).
ovarian carcinoma (continued). "Through analyzing the GEPIA database we found that TRIM71 is overexpressed in HCC, acute myeloid leukemia (AML), testicular germ cell tumors (TGCT), and ovarian cancer (OC)." (PMID 39267787, 2024). "Consistently, ectopic TRIM71 suppressed ovarian cancer cell proliferation in vitro and ovarian tumor growth in vivo, whereas RNAi- or CRISPR-Cas9-mediated ablation of endogenous TRIM71 promoted ovarian cancer cell growth and migration in vitro and/or in vivo." (PMID 31570706, 2019).
Infertility (3 papers, 2021 to 2022). "Last, via exome sequencing analysis, we identified several TRIM71 variants in a cohort of infertile men, including a loss-of-function variant in a patient with an SCO phenotype." (PMID 34055789, 2021). "We showed that germline-specific ablation of Trim71 early in mouse development causes a substantial reduction of gonad size and infertility in both sexes." (PMID 34055789, 2021). "Future unraveling of the molecular mechanisms by which TRIM71 governs germ cell biology will shed further light on the underlying causes of infertility." (PMID 34055789, 2021). "In contrast to the convincing relevance of the TRIM71 LoF variant, assessing the role of the identified rare TRIM71 missense variants in infertile patients of varying histological phenotypes is much more challenging." (PMID 34055789, 2021). "Future experiments should determine whether the here identified missense variants impair other known TRIM71 functions (e.g., TRIM71’s E3 ubiquitin ligase role) as well as determine their pathogenicity in the context of human infertility." (PMID 34055789, 2021). "To investigate the origin of infertility in Trim71 cKO mice, we first analyzed available datasets for the expression of Trim71 in murine male and female gonads." (PMID 34055789, 2021). "As Nanos3 expression in mice embryos is detected as early as E7.5 during PGC specification, the infertility observed in both male and female Trim71 cKO mice may reflect a function of TRIM71 in an early stage of germ cell development." (PMID 34055789, 2021). "Trim71 deficiency in the germline results in infertility in both sexes, as neither cKO males nor females were able to produce offspring after numerous mating attempts over the course of several months." (PMID 34055789, 2021). "However, early developmental defects are likely amplified during postnatal mitotic reactivation and pubertal spermatogenesis as described by a recent work showing infertility in a different germline-specific Trim71 knockout (Trim71–/fl; Ddx4Cre/+) mouse model." (PMID 34055789, 2021). "Our in vitro assays consistently showed TRIM71-dependent changes in cell proliferation as well as in the expression of important PGC regulatory factors, suggesting that infertility in Trim71 cKO mice may be caused by an impaired proliferation of germ cells." (PMID 34055789, 2021). "This search revealed that in the case of NANOS1 overexpression, three infertility related genes (CREBBP, CCNB1, and NPAS2) and five cancer-germ cell genes (CENPL, ERCC6L, KIF18A, SIAH1, and TRIM71) were present in three clusters." (PMID 35743036, 2022).
non-small cell lung carcinoma (3 papers, 2016 to 2022). A group of at least three distinct histological types of lung cancer, including non-small cell squamous cell carcinoma, adenocarcinoma, and large cell carcinoma. "In this study, we demonstrate that TRIM71 expression in non-small cell lung cancer (NSCLC) is associated with tumor size, lymph node metastasis, TNM stage, and poor prognosis." (PMID 29541383, 2018). "In contrast, overexpression of TRIM71 in non-small cell lung carcinoma (NSCLC) cells, in which the LIN28B–let-7–HMGA2 pathway was conserved, decreased cancer cell phenotypes." (PMID 35806250, 2022). "Conversely, overexpression of wild-type TRIM71 in non-small cell lung carcinoma (NSCLC) cells in which Lin28B-let-7-HMGA2 signaling was conserved decreased both cancer cell phenotypes." (PMID 27821801, 2016).
acute myeloid leukemia (2 papers, 2022 to 2024). Acute myeloid leukemia (AML) is a group of neoplasms arising from precursor cells committed to the myeloid cell-line differentiation. "In this context, SMARCA5 regulates the access to DNA and is upregulated in acute myeloid leukemia, while TRIM71 is a post-transcriptional repressor involved in the cell cycle maintaining embryonic stem cell growth and in the processing of the presentation of class I MHC-mediated antigen." (PMID 35740429, 2022).
kidney cancer (2 papers, 2019 to 2021). Primary or metastatic malignant neoplasm involving the kidney. "TRIM71 is frequently under-expressed in human cervix, esophagus, lung and kidney cancer, but no significant prognostic clinical value could be attributed to TRIM71." (PMID 33670160, 2021).
ovarian tumor (2 papers, 2019 to 2020). "To further expand the biological significance of our findings, we established ovarian tumor xenograft models by subcutaneously inoculating ES-2 cells with stably overexpressed or depleted TRIM71 into nude mice." (PMID 31570706, 2019).
viral infection (2 papers, 2025). "Finally, we found that during viral infection, the overexpression of TRIM71 stabilized IRF3, and TRIM71 knockout inhibited the stabilization of IRF3." (PMID 39702801, 2025). "Finally, further examination of RNA-seq data showed downregulation of TRIM71 mRNA (log2FC -0.38), highlighting the dynamic response of host cellular machinery to viral infection." (PMID 40219968, 2025). "DYRK4 acts as a scaffold protein to recruit TRIM71 to interact with IRF3, increasing IRF3 linear ubiquitination, maintaining IRF3 stability during viral infection, and promoting IRF3-mediated antiviral responses." (PMID 39702801, 2025). "DYRK4 acts as a scaffold protein to recruit TRIM71 and LUBAC to IRF3, thereby increasing its linear ubiquitination, maintaining IRF3 stability and activation during viral infection, and promoting the IRF3-mediated antiviral response." (PMID 39702801, 2025). "The underlying mechanism involves DYRK4 acting as a scaffold protein to recruit TRIM71 and LUBAC to IRF3, increasing IRF3 linear ubiquitination, maintaining IRF3 stability and activation during viral infection, and promoting the IRF3-mediated antiviral response." (PMID 39702801, 2025).
breast tumor (1 paper, 2022). "For example, tripartite motif containing 71 (TRIM71), an E3 ligase that was inactivated by phosphorylation via protein kinase A, ubiquitinated pRb and accelerated its degradation in a K48-linked polyubiquitination fashion, which facilitated breast tumor progression." (PMID 35650644, 2022).
Chorangioma (1 paper, 2026). "Chorangioma-affected tissue harbored pathogenic COL1A1, FBXO11, and TRIM71 somatic mutations, with elevated Leptin expression and oxidative stress signatures." (PMID 41634840, 2026).
colon cancer (1 paper, 2019). "Consistent with our findings, TRIM71 has also been shown to have a tumor suppressive role in lung and colon cancer cells by mediating degradation of LIN28B and consequently upregulating the tumor suppressive microRNA let-738,39." (PMID 31570706, 2019).
Cryptozoospermia (1 paper, 2021). A type of oligozoospermia in which spermatozoa can be detected in an ejaculate only after centrifugation and inspection of the pellet. "SYCP2 was recently associated with male infertility, and it is thus unlikely that this patient’s TRIM71 variant alone is responsible for his cryptozoospermia, but an oligogenic cause of his phenotype cannot be ruled out." (PMID 34055789, 2021).
lung squamous cell carcinoma (1 paper, 2018). "In lung squamous cell carcinoma and adenocarcinoma, TRIM71 was localized in the cytoplasm and was significantly upregulated compared with that in normal lung tissues, alveoli, and bronchi tissues." (PMID 29541383, 2018). "In normal lung tissues, TRIM71 expression was very low or absent; in contrast, of the 282 cases of lung squamous cell carcinoma and adenocarcinoma, only 39 were TRIM71-negative." (PMID 29541383, 2018).
male infertility (1 paper, 2021). The inability of the male to effect fertilization of an ovum after a specified period of unprotected intercourse. "Collectively, our analysis leaves the TRIM71 variants c.368T>C/p.(Val123Ala) and c.803T>A/p.(Leu268His) as the likeliest candidates for being associated with male infertility." (PMID 34055789, 2021). "Our work here identifies TRIM71 as a novel gene associated with human male infertility and uncovers a novel role for TRIM71 in the embryonic development of the germline." (PMID 34055789, 2021). "Via this independent and unbiased approach, we found TRIM71 to be present among these genes, revealing a possible association with human male infertility." (PMID 34055789, 2021). "Altogether, our work reveals for the first time an association of TRIM71 deficiency with human male infertility, and uncovers further developmental roles for TRIM71 in the germline during mouse embryogenesis." (PMID 34055789, 2021). "As an additional line of evidence, all patients carrying variants in TRIM71 were evaluated for relevant variants in other genes previously reported in association with male infertility (n = 181)." (PMID 34055789, 2021). "Four of the TRIM71 missense variants identified in infertile men were also found in control subjects with complete spermatogenesis (n = 89) or in a Dutch cohort of proven fathers (n = 5784), making their association with male infertility rather unlikely (green)." (PMID 34055789, 2021). "This constitutes a significant enrichment of TRIM71 LoF variants in the MERGE cohort (n = 908; p = 0.01) and an even higher enrichment in the SCO subcohort (n = 247; p = 0.004), supporting a reliable association of TRIM71 LoF variants with human male infertility." (PMID 34055789, 2021).
neuroblastoma (1 paper, 2016). Neuroblastoma (NB) is the most common solid, extracranial childhood tumor. "Lin28B, a specific substrate of TRIM71, has been reported to function as an oncogenic protein that promotes in vitro transformation of primary cells and tumorigenesis in various models of neuroblastoma, breast epithelial, and intestinal epithelial cancer." (PMID 27821801, 2016).
seminoma (1 paper, 2021). A radiosensitive malignant germ cell tumor found in the testis (especially undescended), and extragonadal sites (anterior mediastinum and pineal gland). "Since we have shown that TRIM71 controls proliferation of seminoma TCam-2 cells, we evaluated whether TRIM71 could also control proliferation in the GCT-derived non-seminoma cell line NCCIT." (PMID 34055789, 2021). "Furthermore, we used the human GCT-derived seminoma cell line TCam-2 as a surrogate in vitro model of PGCs and evaluated cell proliferation upon TRIM71 knockdown." (PMID 34055789, 2021). "Additionally, in vitro growth competition assays, as well as proliferation assays with wild type and CRISPR/Cas9-generated TRIM71 mutant NCCIT cells showed that TRIM71 also promotes proliferation in this malignant GCT-derived non-seminoma cell line." (PMID 34055789, 2021). "Furthermore, TCam-2 cells, a human GCT-derived seminoma cell line which was used as an in vitro model for PGCs, showed proliferation defects upon TRIM71 knockdown." (PMID 34055789, 2021).
thyroid carcinomas (1 paper, 2019). "We then performed the Kaplan–Meier survival analysis (kmplot.com) and found that the higher level of TRIM71 is associated with favorable prognosis of cervix, head and neck, kidney, pancreas, thymus, and thyroid carcinomas." (PMID 31570706, 2019).
Ventriculomegaly (1 paper, 2023). An increase in size of the ventricular system of the brain. "A mouse model harboring a CH-associated mutation in Trim71 (R595H, homolog of human R608H-TRIM71) showed ventriculomegaly with increased intracranial volume, which phenocopied pathological features of patients with CH." (PMID 36757939, 2023).